PCDHGA11 (protocadherin gamma subfamily A, 11)
Description:
Potential calcium-dependent cell-adhesion protein. May be involved in the establishment and maintenance of specific neuronal connections in the brain.
Synonyms: PCDH-gamma-A11
Tractability: Antibody: UniProt places it where antibodies can reach, with medium confidence; UniProt predicts a signal peptide or a membrane-spanning region; its Gene Ontology location is reachable by antibodies, with medium confidence.
Gene: Protein-coding gene on chromosome 5 (141,421,047 to 141,512,975, forward strand). Ensembl gene ENSG00000253873.
Subcellular location: Cell membrane
Subcellular location (Human Protein Atlas): Plasma membrane; Cytosol; Nucleoplasm; Vesicles
Gene Ontology:
Molecular function: cell adhesion molecule binding; calcium ion binding
Biological process: cell adhesion; homophilic cell-cell adhesion
Cellular component: plasma membrane; membrane
Genetic constraint (gnomAD): Loss-of-function variants: 39 observed, 63.07 expected, observed/expected ratio (o/e) 0.62, 90% interval 0.48 to 0.81. The upper end of that interval is the gene's LOEUF score, 0.81, which puts it in group 3 of 6, group 1 being the genes least tolerant of losing a copy. Missense variants: 1,165 observed, 1,265.4 expected, observed/expected ratio (o/e) 0.92, 90% interval 0.88 to 0.97. Synonymous variants: 533 observed, 544 expected, observed/expected ratio (o/e) 0.98, 90% interval 0.91 to 1.05.
Homologues: Orthologues: mouse Pcdhga11 (83% identical). Paralogues in human: PCDHGA12 (76% identical), PCDHGA10 (75% identical), PCDHGA3 (74% identical), PCDHGA5 (74% identical), PCDHGA8 (74% identical), PCDHGA4 (73% identical), PCDHGA6 (73% identical), PCDHGA7 (73% identical), PCDHGA1 (73% identical), PCDHGA9 (72% identical), PCDHGA2 (71% identical), PCDHGB5 (52% identical), and 49 more.
Diseases named in the same sentence as PCDHGA11 in open-access papers:
PCDHGA11 is named in the same sentence as 7 diseases in open-access papers, as found by Europe PMC text mining. Sharing a sentence is not in itself a finding about the gene and the disease. The quoted sentences say what the papers report.
astrocytomas (4 papers, 2019 to 2022). "Additionally, Pcdhga11 and Pcdhb genes were shown to be aberrantly methylated in astrocytomas and neuroblastoma." (PMID 30531834, 2019). "Moreover, these authors found a significant correlation between PCDHGA11 hypermethylation and downregulation in astrocytomas and glioma cell lines." (PMID 31288858, 2019). "Their results show that 82% of grade II astrocytomas, 80% of grade III astrocytomas and 74% of WHO grade IV gliomas showed non- or low expression of PCDHGA11 compared to the average of five normal brain tissue samples." (PMID 35454784, 2022).
glioma (3 papers, 2019 to 2022). A benign or malignant brain and spinal cord tumor that arises from glial cells (astrocytes, oligodendrocytes, ependymal cells). "However, interestingly, they also observed that PCDHGA11 expression was significantly upregulated in several G4 samples, including and especially in recurrent glioma." (PMID 35454784, 2022).
depression (1 paper, 2019). "A rat model of depression revealed that Pcdhga11 expression levels were increased in the hippocampus, suggesting Pcdhga11 could be used as a putative biomarker." (PMID 31019524, 2019).
tumor (2 papers, 2016 to 2021). "Downregulation of cell-cell contact to facilitate EMT and tumor mass blood transport is achieved by deletion of epithelial cell adhesion regulatory genes that include GP1BB and PCDHGA11 in our resultant deleted genes list." (PMID 27136531, 2016).
PCDHGA11 also shares sentences with these, for which no sentence is quoted: glioblastoma (1 paper); neuroblastoma (1); Sotos syndrome (1).